TLR4 (toll like receptor 4)
Diseases named in the same sentence as TLR4 in open-access papers (continued):
Sharing a sentence is not in itself a finding about the gene and the disease.
Hyperglycemia (121 papers, 2010 to 2026). An increased concentration of glucose in the blood. "Mechanistically, we unraveled that while TLR4 in BM-derived immune cells mediates the hyperglycemia-improving effect of r-mS100A9 within the SkM, TLR4 in KCs underlies the hyperketonemia- and hypertriglyceridemia-lowering action of S100A9 in the liver." (PMID 40874857, 2025). "Hyperglycemia induces innate immune activation via increased levels of Toll-like receptor 4 (TLR4), which is associated with the pathogenesis of DR, and the TLR4 genetic polymorphisms in humans are associated with DR risk." (PMID 39457089, 2024). "Hyperglycemia leads to an increase in the mRNA and protein expression of TLR4 in the monocytes, and TLR4 deficiency can inhibit the high glucose-induced inflammatory response." (PMID 38275739, 2024). "Hyperglycemia-induced upregulation of TLR4 is associated with increased NADPH oxidase activity via protein kinase C." (PMID 36619717, 2022). "It was found that suppression of hyperglycemia-induced apoptosis by TLR4 is associated with attenuation of ROS production." (PMID 34299310, 2021). "As expected, leptin therapy improved the hyperglycemia and hyperketonemia caused by ID in Tlr4+/+ controls; yet, similar outcomes were observed in insulin deficient Tlr4−/− mice." (PMID 31391467, 2019). "It has been previously reported that hyperglycemia-induced TLR-4 stimulation creates an inflammatory milieu, and causes recruitment of monocytes, hence stimulates IL-6 secretion." (PMID 30534206, 2018). "Hyperglycemia-induced TLR4 expression in human monocytes is associated with increased NAPDH oxidase activity triggered by PKC." (PMID 26468333, 2015). "Hyperglycemia-induced inflammation causes the dysfunction of blood vessels, and Toll-like receptor 4 (TLR4) plays a key role in inflammation-induced angiogenesis." (PMID 26468333, 2015). "TLR4 deficiency resulted in inhibition of reactive oxygen species (ROS) production and NADPH oxidase activity, suggesting suppression of hyperglycemia-induced apoptosis by TLR4 is associated with attenuation of oxidative stress to the cardiomyocytes." (PMID 21159162, 2010). "Therefore, the TLR4/p38 pathway may be a potential therapeutic target for controlling hyperglycemia‐associated microglia activation and neuroinflammation." (PMID 35478445, 2022). "TLR4, a member of the TLRs, might be a molecular link between chronic inflammation and metabolic syndrome associated disorders such as hyperglycemia, dyslipidemia, and hemodynamic abnormalities, which have been implicated to be the risk factors contributing to DN." (PMID 26347890, 2015). "Taken together, these data suggest that rTMD1 confers general anti‐inflammatory, pro‐repair benefits and, in the diabetic cornea, specifically corrects hyperglycemia‐sensitive HMGB1/TLR4/NLRP3 signaling to facilitate reepithelialization." (PMID 41503166, 2026). "At the molecular level, several lines of evidence indicate that Schwann cells exposed to hyperglycemia undergo oxidative stress and inflammation mediated by TLR4/NF-κB, with reduced Nrf2 activity, which favors apoptosis and myelin loss." (PMID 41465799, 2025). "This increase in TLR2 and TLR4 activity is accompanied by a pro-inflammatory state and hyperglycemia." (PMID 40076851, 2025). "Taken together, our results demonstrate that immune cell TLR4 is sufficient for r-mS100A9 to lower hyperglycemia and enhance SkM glucose uptake." (PMID 40874857, 2025). "Female mice developed less severe hyperglycemia and were resistant to neuropathic changes, making the protective effects of TLR4 deletion less pronounced in females than in males." (PMID 41167527, 2025). "Hyperglycemia can promote the activation of TLR4, NF-κB pathway and NLRP3, and the subsequent inflammatory and fibrosis reactions, resulting in the emergence of diabetic nephropathy." (PMID 40176887, 2025).
Hyperglycemia (continued). "In the current study, the role of TLR4/NF-κB cascades, triggered by hyperglycemia and ROS, in significantly influencing AGE activation in DCM has been emphasized." (PMID 40737341, 2025). "TLR4 signaling emerges as a central mediator in the hyperglycemia-induced tendon pathology observed in this study." (PMID 40855901, 2025). "The gene and protein expression levels of TLR4 were synergistically elevated by the combination of hyperglycaemia and oxLDL treatment." (PMID 38525707, 2024). "We report, for the first time, that exposure to hyperglycaemia induces a synergistic effect on oxLDL-induced apoptosis via the TLR4 pathway in Schwann cells." (PMID 38525707, 2024). "TLR4-mediated inflammation drives the synergistic effect of hypoxia and hyperglycemia on impaired diabetic wound healing." (PMID 38950058, 2024). "Pre-treatment with TAK-242, a selective toll-like receptor 4 signalling inhibitor, attenuated hyperglycaemia- and oxidised low-density lipoprotein-induced cell death and apoptotic caspase-3 pathway." (PMID 38525707, 2024). "Subsequently, we tested the effect of hyperglycaemia on TLR4 expression in oxLDL-treated IMS32 cells." (PMID 38525707, 2024). "Hyperglycaemia-induced increased levels of TLR4 and HMGB1 are inhibited by the application of the Box A portion of HMGB1 and glycyrrhizin in both cultured human REC and mouse retina." (PMID 38983565, 2022). "TLR4 signalling in RECs is attenuated by exchange protein activated by cAMP 1 (Epac1) leading to inhibition of hyperglycaemia induced MyD88-mediated signalling, suggesting that Epac1 acts upstream of TLR4 dependent signalling." (PMID 38983565, 2022). "Gastrodin inhibits hyperglycaemia induced HREC apoptosis by regulation of SIRT-1 induced inhibition of TLR4 signalling mechanisms." (PMID 38983565, 2022). "We previously found that melatonin can alleviate hyperglycemia-induced renal inflammation by inhibiting the activation of TLR4 and the TGF-β1/Smad3 signaling pathway." (PMID 35979396, 2022). "Recent research revealed that toll-like receptor 4 (TLR4) expression was upregulated under hyperglycemia." (PMID 36148071, 2022). "Hyperglycaemia (HG) exacerbates myocardial ischaemia/reperfusion (I/R) injury with the activation of HMGB1‐RAGE/TLR2/TLR4‐NF‐κB signalling, which is reversed by ethyl pyruvate (EP) treatment." (PMID 35706377, 2022). "Hyperglycaemia is also associated with hREC apoptosis, reduced RPE viability and raised levels of TLR4 and NF-κB in HRECs." (PMID 38983565, 2022). "Pae inhibits MMP-9 expression and the inflammatory response in hyperglycemia-induced retinal microglia via inhibition of the TLR4/NF-κB signaling pathway, through the upregulation of suppressor of cytokine signaling 3 in diabetic retinopathy." (PMID 35184653, 2022). "Microglial matrix metalloproteinase 9 (MMP-9) levels are raised in response to hyperglycaemia via HMGB1/TLR4 signalling in BV2 murine glial cells." (PMID 38983565, 2022). "The expression of TLR4 is increased in the immune cells of diabetic patients and is probably activated by hyperglycaemia." (PMID 35419168, 2022). "Current evidence also supports potential protective mechanisms of prostasin against hyperglycaemia, including that mediated by TLR4." (PMID 35922613, 2022). "The change in seizure rate, hyperglycemia, and the whole used TLR4 as the target to construct a short hairpin shRNA plasmid." (PMID 36619717, 2022). "Previous researches are in line with our results, and TLR4/IRAK1/TRAF6/NF-κB pathway was markedly activated under hyperglycemia." (PMID 36148071, 2022). "Zhang and colleagues demonstrated that the decrement of TLR4 reduced hyperglycemia-induced osteoblast apoptosis, promoted bone mineralization, and improved bone structure in a rat model." (PMID 35237235, 2022). "Apocynin reduces hyperglycaemia induced retinal apoptosis, restores retinal morphology, and reduces oxidative stress through what was presumed to be via TLR4-NF-kB signalling axis." (PMID 38983565, 2022).
Hyperglycemia (continued). "Hyperglycemia-induced TLR4 activation can influence the activity of NADPH in mitochondria, promote the production of reactive oxygen species and ultimately result in apoptosis by disrupting the balance between autophagy and apoptosis." (PMID 33795817, 2021). "Herein, we determined TLR4 protein and mRNA expression in macrophages cultured under hypo- and hyperglycemia (RIH)." (PMID 32806763, 2020). "Free fatty acids exacerbate the inflammatory response by engaging TLR4 in macrophages, while hyperglycemia accelerates the production of AGEs, which also elicit the M1 macrophage polarization." (PMID 32964051, 2020). "Despite similar levels of hyperglycemia and similar daily insulin doses, only in progressors was activation of the NF-κB pathway observed, as indicated by the overexpression of TLR4, nuclear p65 and IL-6." (PMID 32116790, 2020). "Hyperglycemia activates toll-like receptor 4 (TLR4) to induce inflammation in diabetic cardiomyopathy (DCM)." (PMID 32358497, 2020). "ZDF animals with Type 2 diabetic painful neuropathy revealed a significant increase in NLRP3, HMGB1, and TLR4 in DRG at eight weeks after hyperglycemia when compared to their control counterparts." (PMID 32019145, 2020). "While previous studies have demonstrated that hyperglycemia modulates the expression levels of TLR4 in the aorta of STZ-induced diabetic animals, we did not observe differences in the expression levels of this receptor." (PMID 32694567, 2020). "Over accumulation of tissue palmitic acid results in dyslipidemia, hyperglycemia, increased ectopic fat accumulation, increased inflammatory tone via toll-like receptor 4 as well as pro-inflammatory adipokines mRNA expression in macrophages." (PMID 33059653, 2020). "Together with TLR4-LPS pathway modification, hyperglycaemia did alter the secretion of some inflammatory mediators." (PMID 31391499, 2019). "In order to investigate the mechanism for the effect of TLR4/NF-κB on the mitochondria-related tubular oxidative damage in hyperglycemia, we inhibited the expression of TLR4 or NF-κB in vivo and in vitro." (PMID 29861832, 2018). "In recent years, free fatty acid-bound fetuin-A has been shown to be an endogenous ligand for toll-like receptor 4 (TLR4), and hyperglycemia has been shown to enhance IL-1β secretion." (PMID 28299342, 2017). "Under conditions of hyperglycemia, the OR (95% CI) was 4.905 (1.640–14.673) between TLR4 rs11536889 and MyD88 rs7744 (p value for interaction = 0.004)." (PMID 26959040, 2016). "In the current study, heterogeneity in the hyperglycemia or hyperlipidemia status of the study participants had a significant effect on the interaction of TLR4 rs11536889 and MyD88 rs7744." (PMID 26959040, 2016). "In conditions of hyperglycemia, the interaction effect was strengthened between TLR4 rs11536889 and MyD88 rs7744 (p value for interaction = 0.004)." (PMID 26959040, 2016). "Increased TLR4 level in placentae was correlated with higher maternal hyperglycemia, which partly reflected a heightened whole body IR." (PMID 27340831, 2016). "It is reported that hyperglycemia induces TLR4 expression in hyperglycemic human retinal endothelial cells." (PMID 26468333, 2015). "Our results revealed that hyperglycemia induced overexpression and activation of TLR4 in endothelial cells." (PMID 26468333, 2015). "WT and TLR4−/− mice treated with STZ displayed a similar profile in the progression of hyperglycemia and changes of body weight over a 24 week period." (PMID 24842252, 2014). "TLR4 gene expression and activation have been demonstrated to be increased in the monocytes of patients with hyperglycemia." (PMID 24348797, 2014). "Different studies in T1DM mice models show that TLR4 silencing prevents cardiac lipid accumulation, hyperglycemia-induced myocardial apoptosis, and ventricular remodeling and dysfunction." (PMID 24744784, 2014). "Hyperglycemia is known to promote TLR4 expression in monocytes from patients with type 1 and 2 diabetes." (PMID 24842252, 2014).
Hyperglycemia (continued). "Even though hyperglycemia promoted the mRNA expression of IL-8 or TLR4 and PMN aggregation, it diminished the MPO activity in the lung tissue." (PMID 23622115, 2013). "At the onset of hyperglycemia, the levels of IL-1β and inflammatory responses such as TLR4, COX1, COX2, NF-κB, CD45, and iNOS were increased in the hippocampus." (PMID 22844396, 2012). "Treatment with TLR4 siRNA prevented hyperglycemia-induced apoptosis, highlighting a novel RNAi-based therapy for diabetic cardiac complications using TLR4 siRNA." (PMID 21159162, 2010). "After 7 days of hyperglycemia, the level of TLR4 mRNA in myocardial tissue was significantly elevated." (PMID 21159162, 2010). "Significantly increased TLR4 was detected in the myocardial tissue of STZ-mice as early as 3 days after the appearance of hyperglycemia." (PMID 21159162, 2010). "Moreover, hyperglycemia can directly induce a reduction in testosterone production by activating the Toll like receptor-4 (TLR-4) mediated oxidative stress pathway." (PMID 40061456, 2025). "Hence, these findings indicate that hyperglycaemia and oxLDL treatment induce the hyperactivation of TLR4 signalling, leading to Schwann cell apoptosis." (PMID 38525707, 2024). "Hyperglycaemia reportedly increased TLR4 expression in monocytes and renal proximal tubular cells." (PMID 38525707, 2024). "In another study, deletion of the TLR4 gene in mice attenuated hypercholesterolemia and hyperglycemia, suggesting that TLR4 could be a target for preventing MS." (PMID 39459627, 2024). "Once these toxins enter the bloodstream, they bind to cluster of differentiation 14 (CD14) on macrophages and monocytes and are recognized by toll-like receptor 4 (TLR4), which exacerbates metaflammation and promotes liver damage, leading to a vicious cycle of hyperglycemia and dyslipidemia." (PMID 39275295, 2024). "Additionally, the inhibition of TLR4/NF-κB activation can block glucose production in several hepatocyte cells and further inhibit the occurrence of hyperglycemia." (PMID 38275739, 2024). "Our findings suggest that the hyperactivation of toll-like receptor 4 signalling by hyperglycaemia and elevated oxidised low-density lipoprotein levels synergistically exacerbated diabetic neuropathy; thus, it can be a potential therapeutic target for diabetic neuropathy." (PMID 38525707, 2024). "We tested our hypothesis that the increase in cell death induced by the combination of hyperglycaemia and oxLDL treatment was due to the hyperactivation of the TLR4 pathway." (PMID 38525707, 2024). "Hyperglycemia enhances the expression and activation of Toll-like receptor 4 (TLR4) in human endothelial cells that may play an important role in DR." (PMID 37371657, 2023). "Moreover, hyperglycemia can directly induce a decrease in Leydig’s cells-produced testosterone via activating the TLR4-mediated oxidative stress pathway." (PMID 37361537, 2023). "Hyperglycemia has been shown to upregulate TLR4, leading to excessive inflammatory reactions." (PMID 36619717, 2022). "It indicates that hyperglycemia activated the TLR4 pathway during wound healing." (PMID 35463063, 2022). "However, in diabetic animals, hyperglycemia and ischemia lead to a significant increase in the expression and activation of TLR4, thereby promoting inflammation through downstream cytokines (such as IL-6)." (PMID 35463063, 2022). "Based on these findings, hyperglycemia may activate TLR4 through endogenous HSPs, thereby stimulating the inflammatory response of cardiomyocytes." (PMID 36114541, 2022). "Hyperglycaemia induced impairment of the insulin receptor and Akt phosphorylation in rMC-1-O (rat Muller) cells is reduced on the administration of TLR4 siRNA, implying high glucose induces dysfunctional insulin signalling via TLR4 in retinal Muller cells." (PMID 38983565, 2022).
Hyperglycemia (continued). "Disproportionate energy balance might disrupt the tightly controlled regulation of tissue PA, thus leading to dyslipidemia, hyperglycemia, and ectopic fat accumulation, and activate the inflammatory TLR4/NF-ĸB-p65 pathways." (PMID 34294819, 2021). "However, the study of Mo has found that using NADPH and PKC inhibitors to down-regulate the expression of TLR2 and TLR4 can improve the continuous inflammation induced by hyperglycemia." (PMID 33967796, 2021). "While there is still extensive debate about the mechanism leading to TLR4 activation during type 1 diabetes, it seems that sustained hyperglycemia drives the generation of DAMPs, which, in turn, signal through this receptor leading to an increase in oxidative stress." (PMID 32694567, 2020). "We further show that expression of the innate immune TLR4 receptor was enhanced in THP-1 macrophages exposed to RIH as compared to normoglycemia while it matched with the TLR4 expression induced by persistent hyperglycemia at a glucose concentration of 15 mM/L." (PMID 32806763, 2020). "TLR4, an important regulator of the NF-κB signaling pathway, has been shown to regulate cell apoptosis, inflammatory response and oxidative damage of renal tubular epithelial cell in hyperglycemia." (PMID 32073611, 2020). "Moreover, in vitro hyperglycemia induced TLR-4 expression via PKC leading to increased levels of IL-6 and chemokine (CC motif) chemokine ligand 2 (CCL-2), via IkB/NF-kB pathway." (PMID 31835864, 2019). "Hyperglycemia alone, without I/R injury, caused significant increases in TLR4 and nuclear NF-κB levels compared with the NS group (p < .05), which clarified the consistent increases in pro-inflammatory cytokines levels." (PMID 31441362, 2019). "Besides hyperglycemia and ROS, apoptosis can be triggered by an activation of Toll-Like Receptor 4 (TLR4)." (PMID 29371661, 2018). "The hypothesis of this study was that miR-146a plays a key role in attenuating hyperglycemia-induced inflammatory pathways through reduced TLR4/NF-κB and TNFα signaling in primary human retinal microvascular endothelial cells (REC)." (PMID 26997759, 2016). "Furthermore, the expression of TLR4 is positively correlated with local IR in placentae and maternal hyperglycemia." (PMID 27340831, 2016). "In the present study, we tested the hypothesis that overexpression of miR-146a protects REC from hyperglycemia-induced proinflammatory responses through downregulation of TLR4, NF-κB, and TNFα." (PMID 26997759, 2016). "Hyperglycemia and free fatty acids (FFAs) synergistically promoted oxidative stress to aggravated the dysfunction of endothelia and insulin resistance, which are mediated by activated TLR4." (PMID 26468333, 2015). "In addition, after 16 weeks on a HFD, control mice developed mild hyperglycemia while TLR4-mutant mice remained euglycemic." (PMID 26539824, 2015). "Our study demonstrated that hyperglycemia enhances the expression of TLR4 and activates TLR4 in human endothelial cells that may play an important role in diabetic retinopathy." (PMID 26468333, 2015). "In vitro, TLR4 expression and activity were increased under hyperglycemia in mesangial cells and could contribute to the progression of diabetic nephropathy." (PMID 24779014, 2014). "Second, hyperglycemia in itself induces the expression of TLR4 mRNA." (PMID 23622115, 2013). "We found that hyperglycemia enhanced inflammatory responses in the acutely injured lung and that inhaled insulin ameliorated these responses, as shown in reduction of IL-8 and TLR4 mRNA expressions in the BALF cells, even greater than those treated by intravenous insulin." (PMID 23622115, 2013). "In summary, this study defined the role of TLR4 in hyperglycemia-induced apoptosis in STZ mice." (PMID 21159162, 2010).